CD276 (CD276 molecule)
Diseases named in the same sentence as CD276 in open-access papers (continued):
Sharing a sentence is not in itself a finding about the gene and the disease.
cancer (continued). "In addition to CD276 (B7-H3), FLT1 (VEGFR1) appeared in both C3 and C4 networks and was highly expressed in ACC compared with that in other cancers." (PMID 34194394, 2021). "B7-H3 (also known as CD276) is a newly found molecule of B7 family, which may be a promising target for cancer treatment." (PMID 32398947, 2020). "B7-H3 (CD276) is an immune checkpoint from the B7 family of ligands, many of whom interact with known checkpoint markers including CTLA-4, PD-1, and CD28 and it is overexpressed in many cancer types." (PMID 32894202, 2020). "The other molecules involved in immune-inhibitory pathways, such as lymphocyte activation gene-3 (LAG-3, CD223), T cell immunoglobulin-3 (TIM-3), and B7 homolog 3 (B7-H3, CD276), which are considered potential targets of cancer immunotherapy, can also be targeted by antibodies." (PMID 30658461, 2019). "CD276, as an immunoregulatory molecule, plays immunological and non-immunological roles in different types of human cancer including CRC." (PMID 27329595, 2016). "These outliers (CD276, VTCN1) were present in all three cancer subtypes." (PMID 27683114, 2016). "B7 homologous protein 3 (B7-H3, also known as CD276), a newly discovered member of the B7 family, is an immunomodulatory protein with co-stimulatory/co-inhibitory effects and is an attractive and promising target for cancer immunotherapy, playing a dual role in the immune system." (PMID 40356928, 2025). "Previous studies have shown that CD276 upregulation promotes the expression of stem cell markers, such as Prominin 1 (PROM1/CD133), CD44, and POU Class 5 Homeobox 1 (POU5F1/Oct4), potentially facilitating the epithelial–mesenchymal transition (EMT) in certain cancers." (PMID 40136662, 2025). "Similarly, ZNF668 was positively correlated with PVRL2 (Nectin-2), CD276 (B7-H3), TGFB1, and multiple members of the TNF receptor superfamily, including TNFRSF4 (OX40), TNFRSF18 (GITR), and TNFRSF25, in the vast majority of analyzed cancers." (PMID 41614761, 2025). "CD276 is overexpressed in cancer cells, inhibits T-cell activation, and has nonimmune functions." (PMID 39781264, 2025). "Additionally, the KEGG enrichment analysis indicated that “Proteoglycans in cancer”, “Focal adhesion”, “ECM-receptor interaction”, and the “PI3K-Akt signaling pathway” might be involved in CD276-mediated TME reconstruction." (PMID 39766794, 2024). "In addition, CD276 is thought to have non-immunological roles in cancer progression by activation of proliferation, invasion, metastasis, and resistance to chemotherapy." (PMID 38561369, 2024). "Furthermore, CD276 expression was significantly correlated with chemokine receptor genes, including CCR1 [chemokine (C-C motif) receptor 1], in the KICH, LGG, LIHC and THCA cancer types." (PMID 36717836, 2023). "Highly-expressed coagulation fibrinolysis genes, including PLAU, PLAUR, and SERPINE1, are associated with monocytic infiltration and overexpressed immune checkpoints (PD-L2 and CD276/B7-H3) in pan-cancer, indicating that increased PLAU may be related to the TME in cancer." (PMID 38025757, 2023). "Notably, CD276, PGFBI, ENTPDI, and ICAM1 were highly expressed in most of the human cancers." (PMID 36105106, 2022). "In addition, CCNA2 could positively regulate TAP1, TAP2, CD276, MICB, PVR, and ULBP1 in almost all the cancer types." (PMID 35401923, 2022). "We corroborate that the median CD276 expression on the UM-UC cell surfaces was higher when compared to NUCs, but elevated CD276 expression did not correlate with fast cell proliferation in vitro, and nor did the expression of the cancer stem cell markers investigated." (PMID 35563359, 2022). "All in all, no negative effect on CD276-CAR NK-92 cell-mediated cytotoxicity could be demonstrated with variances in acidity, immunosuppressive molecules like TGFβ or co-incubation with cancer-associated fibroblasts." (PMID 33925968, 2021).
cancer (continued). "Notably, an increasing number of studies support a pro-oncogenic role for CD276 in various human cancer types that is independent of its immune function." (PMID 33431797, 2021). "This led on average to a 63% increase in cell lysis rates by CD276-directed CAR NK-92 cells, compared to no changes for anti-HLA-I siRNA treated HLA-Ilow cells (all cancer cells, except for LK7)." (PMID 40469103, 2025). "And the glycogen riskScore was significantly positively related with immunoinhibitors TGFB1, ICAM1 and CD276, and showed significantly negative relationship with immunostimulators TNFSF14 across pan-cancer." (PMID 39895799, 2025). "In terms of immune-activated genes, AURKA exhibited positive correlations with MICB, PVR, CD276, and ULBP1 and negative correlations with C10orf54 in most cancers." (PMID 37965456, 2023). "The co-signal molecule B7-H3 (CD276) is abnormally upregulated in NSCLC and plays a negative role in cancer progression." (PMID 35590371, 2022). "B7-H3 (CD276) is a type I transmembrane protein that plays a critical role in the activation or inhibition of T-cell function, is highly overexpressed in a wide range of cancers and correlates with negative clinical outcomes and poor prognosis." (PMID 36874119, 2023). "In addition, NRP1, CD276, and VSIR showed obvious positive correlation with SLC7A11 expression in most cancers, although the drugs targeted at these checkpoints have not been applied in clinic." (PMID 34938318, 2021). "In addition, N6AMT1 expression had pan-cancer correlations with most of the 45 immunostimulators: in ACC, N6AMT1 expression showed the strongest positive correlation with CXCR4; in UVM, N6AMT1 expression showed the strongest negative correlation with CD276." (PMID 37437243, 2023).
CNS tumors (27 papers, 2020 to 2025). "Many trials investigating CAR-T for ST and CNS tumors focused on cell surface antigens that are expressed at high levels on malignant cells but scarcely discovered in normal tissues, including B7-H3/CD276 and GD2." (PMID 38021600, 2023). "Intriguingly, BrainChild-03 (NCT04185038) delivering CD276 (B7H3) CAR T cells to pediatric patients with CNS tumors does include diagnosis of DIPG or DMG." (PMID 37637064, 2023). "Indeed, there is a CD276 targeting CAR T-cell immunotherapy phase I clinical trial investigation (BrainChild-03) in pediatric CNS tumors open and currently recruiting (NCT04185038)." (PMID 37637064, 2023). "Among them, 124I- and 131I-omburtamab (previously named 8H9), a radiolabeled antibody against B7-H3 (CD276), have shown promise for PET-based dosimetry and targeted treatment in refractory CNS tumors." (PMID 40563556, 2025). "In additional trials, BrainChild-02 (NCT03638167) delivers EGFR-specific CAR T cells to pediatric CNS tumor patients, and BrainChild-03 (NCT04185038), delivered CD276-specifc CAR T cells to pediatric patients with CNS tumors, including DIPG." (PMID 37152812, 2023). "Recently, several studies have proved the overexpression of CD276 on a variety of TME cells, as well as hematologic and solid tumors, including leukemia, prostate cancer, melanoma, neuroblastoma, osteosarcoma, and CNS tumors." (PMID 34163465, 2021).
infection (15 papers, 2009 to 2025). The state of being infected such as from the introduction of a foreign agent such as serum, vaccine, antigenic substance or organism. "Given that the immunomodulatory effects of CD276/CD155 blockade are transient, the primary risk may lie in increased susceptibility to infection during the peri-transplantation period." (PMID 41403780, 2025).
adenocarcinoma (12 papers, 2018 to 2025). A common cancer characterized by the presence of malignant glandular cells. "Elevated CD276 levels correlate with worse overall survival, particularly in adenocarcinoma subtypes, highlighting its relevance in treatment-resistant tumors." (PMID 40821788, 2025).
immune diseases (6 papers, 2021 to 2025). "CD276 plays an important role in the regulation of both autoimmunity and inflammation; therefore, it has been extensively studied as a promising therapeutic target for immune diseases in recent years." (PMID 35836993, 2022).
hematological malignancies (5 papers, 2015 to 2025). "B7-H3 [B7-homolog 3 or CD276] remains poorly investigated in hematological malignancies." (PMID 26376842, 2015).
bacterial infection (2 papers, 2011 to 2024). "In the convalescent phase of bacterial infection, CD45RB, CD276, and CCL27 are downregulated." (PMID 37831367, 2024).
blood cancers (1 paper, 2023). "The immune checkpoint B7-H3 (CD276), a member of the B7 family with immunoregulatory properties, has been identified recently as a novel target for immunotherapy for refractory blood cancers and solid malignant tumors." (PMID 37564196, 2023).
CD276 also shares sentences with these, for which no sentence is quoted: acute myeloid leukemia (19 papers); multiple myeloma (15); asthma (11); chordoma (10); gastric adenocarcinoma (9); pancreatic ductal adenocarcinoma (9); renal carcinoma (9); brain cancer (8); craniopharyngioma (6); pediatric cancers (6); bacterial meningitis (5); bone cancer (5); diabetes (5); ependymoma (5); gastric tumor (5); kidney cancer (5); oral squamous cell carcinoma (5); pneumococcal meningitis (5); rheumatoid arthritis (5); soft tissue sarcoma (5); anaplastic meningioma (4); bone sarcoma (4); gastrointestinal tumors (4); retinoblastoma (4); adenoma (3); allergic asthma (3); alveolar rhabdomyosarcoma (3); Autoimmunity (3); chondrosarcoma (3); COVID-19 (3).
A further 183 diseases each share a sentence with CD276 in 3 papers or fewer.